CD4 (CD4 molecule)
Diseases named in the same sentence as CD4 in open-access papers (continued):
Sharing a sentence is not in itself a finding about the gene and the disease.
tumor (continued). "CXCR6-dependent Recruitment of NKT cells and CD4+ T cells to the liver exerts important functions in tumor surveillance to inhibit hepatocarcinogenesis." (PMID 34983554, 2022). "On the other hand, cDC2 can activate Th1, Th2, Th17, and CD8+ T cells in vitro and drive anti-tumor CD4+ T cell immunity." (PMID 36654820, 2022). "In vivo experiments revealed that transfection with vectors expressing STAT1 and STAT3 inhibited the Siglec-15 RNAi-induced inhibition on tumor growth and the increases in CD4+/CD8+ ratio." (PMID 35769818, 2022). "The peptide group exerted a minute effect on CD4+ T cells in the tumor while CD4+ T cells significantly increased upon combining the peptides with iron particles." (PMID 36291890, 2022). "Tumor-infiltrating CD4+ T cell populations, including CD4+ Treg and CD4+ TN subsets, showed markedly increased Treg scores than those residing in CCs." (PMID 36198671, 2022). "Compared to other immunotherapies targeting specific antigens, it has the advantage of carrying relatively intact tumor antigens and this allows the activation of CD4+ T helper and CD8+ cytotoxic lymphocytes simultaneously." (PMID 36523982, 2022). "While greater attention has been given to the function of CTLs in tumor protection, it has been established that CD4+ helper T cells also have a crucial function in cancer immune responses in both patients and animal models." (PMID 35855850, 2022). "Our results prove that STING is positively correlated with enhanced antitumor CD8+ and CD4+ T-cell infiltration and migration into the tumor and inhibition of myeloid cell polarization into Tregs and M2 macrophages." (PMID 35902768, 2022). "Specifically, 9,603 (60.58%) CD4+ T cells were obtained from tumor tissues, of which 24.21% were from LUAD and 36.37% were from LUSC tissues." (PMID 36008393, 2022). "The results pointed to a pronounced Th17 commitment of CD4+ tumor-infiltrating lymphocytes in untreated GBM patients." (PMID 36539408, 2022). "In this study we demonstrate in a murine model that citrullinated GRP78 is present in tumour samples and we identify a citrullinated GRP78 peptide which binds to and stimulates CD4 T cell responses restricted through multiple HLA alleles." (PMID 36544781, 2022). "The results showed that CDK9 were closely related to lymphocyte infiltration in tumor tissue, such as CD4 + T cells, CD8 + T cells, et, but the expression level of CDK9 was neither increased nor decreased in the CRC." (PMID 35814446, 2022). "The expression of PD-1/PD-L1 as well as tumor-infiltrating CD4, CD8, and CD56 immune cells was examined using multiplex immunofluorescent analysis." (PMID 35311077, 2022). "Tumor-specific CD4 T cells provide signals for CD8 T cells to destroy tumor cells and effectively inhibit tumor development." (PMID 36232485, 2022). "After the systematic review, we concluded that the anti-tumor effect of ICIs is related to the infiltration of both CD4+ and CD8+ T cells in tumors." (PMID 35433707, 2022). "DC are exclusively responsible for cross-presentation of tumor-associated antigens to CD8 T cells and can integrate innate immune signals and CD4 T cell responses to maximize tumor-specific CD8 T cell expansion." (PMID 35937775, 2022). "We then analyzed tumor-infiltrating CD4 T cells and found an increased expression of interferon-beta (Ifnb1) and interferon-stimulated gene (ISG) transcripts (Ccl5, Ifit1, and Mx2) in cells isolated from mice treated with cGAMP compared with controls." (PMID 35091453, 2022). "Recent evidence indicates that CD4+ T cells can target tumor cells in various ways, either directly by eliminating tumor cells or indirectly by modulating the tumor microenvironment." (PMID 35094065, 2022). "The result of tumor immunity analysis indicated that T-cell CD4 memory activated cells were positively correlated to the risk score." (PMID 35211510, 2022).
tumor (continued). "Epigenetic mechanisms triggered by cancer to shape the identity of tumor infiltrating CD4+ T cells within the TIME have been observed in cancer models." (PMID 35805021, 2022). "A total of 83 PrBC and 89 EOBC were selected from our Institutional registry and subjected to tumor-infiltrating lymphocytes (TILs) profiling and immunohistochemistry for CD4, CD8, forkhead box P3 (FOXP3), and programmed death-ligand 1 (PD-L1) (clone 22C3)." (PMID 35892583, 2022). "CD4+ T cells in MM can induce effective antitumor immune responses by interacting with antigen-presenting cells in the tumor microenvironment." (PMID 35401705, 2022). "Afterwards, the exogenous antigens are presented to MHC class II molecules and inform CD4+ T cells to induce tumor-antigen-specific antibodies." (PMID 36298450, 2022). "For instance, GSDME activation suppresses tumor growth by increasing the antitumor properties of tumor-infiltrating NK cells and CD4+ and CD8+ T lymphocytes." (PMID 35844506, 2022). "On the other hand, Treg cells, an immunosuppressive subtype of CD4+ T cells, play an essential role in hindering protective immunosurveillance of neoplasia and hampering effective anti-tumour immune responses." (PMID 35053279, 2022). "The presence of tumors stimulated a large CD4+ T-cell response in the spleen when compared to non-tumor–bearing mice (p < 0.0001); this was unaltered by the use of the immunomodulators." (PMID 35782876, 2022). "Application of mRNAs encoding mutant antigenic epitopes produces intensive antigen-specific CD8+ T cell responses and effective and durable CD4+ T cell-mediated tumor regression." (PMID 35720301, 2022). "Over the past decades, accumulating research has noted the cytotoxic functions of CD4+ T cells in cancers, which displayed heterogeneous phenotypes with functional capacity of direct tumor lysis through MHC class II-dependent pathways." (PMID 35928827, 2022). "As was discussed for human studies and ACT studies, CD4+ T cells can be directly cytotoxic for tumor cells." (PMID 36159781, 2022). "A significant positive correlation was found between the percentage of CD4+IFN-γ+TNF-α− T cell and the tumor size (R = 0.4, P = 0.020), whereas the frequency of CD4+TNF-αhi T cells correlated inversely with the tumor size (R = − 0.3, P = 0.045)." (PMID 36376825, 2022). "On the other hand, surprisingly, adoptive transfer of exogenous activin A-treated DCs or CD4+ T cells prevents tumor cells from growing, which provides a brand new insight on functions of TGF-β superfamily." (PMID 35774793, 2022). "Overall, our results demonstrate that the low levels of tumor-infiltrating CD8+ Teff cells are dominated by CD4+ and CD8+ Tregs in CRC tumors, which display activated phenotypes with immunosuppressive functions." (PMID 35804964, 2022). "Tumor-infiltrating CD4+ and CD8+ T cell functionality was markedly improved only in the combination group, not the monotherapy groups, as shown by increased cytokine production." (PMID 35327475, 2022). "As at the tumor–stroma interface, CD4+ and CD8+ T cells showed perivascular depletion, as did macrophages." (PMID 35437329, 2022). "Second, arm-level gain of DLK2 gene reduced CD8+ T cells (*** p < 0.001), CD4+ T cells (** p < 0.01), macrophage (** p < 0.01), neutrophil (*** p < 0.001), and dendritic cell infiltrations (** p < 0.01) in tumor tissue." (PMID 35456435, 2022). "CD8 lymphocytes destroy tumor cells and CD4+ subpopulations can produce pro- or antitumor responses." (PMID 36551522, 2022). "Next, 22 immune cell infiltration levels also showed a higher proportion of CD4+ T cells resting, NK cells, dendritic cells and neutrophils in the high-risk group, suggesting that these patients may be in a relatively active state of anti-tumor immune response." (PMID 36311764, 2022).
tumor (continued). "Studies have shown that the number and function of tumor-infiltrating CD4+, CD8+, or CD45+ T cells positively influence the prognosis of human cancers." (PMID 36552960, 2022). "Flow cytometry analysis of tumour samples at 24 h post-PIT (18 μg/50 J/cm2) showed higher levels of CD4+ and CD8+ immune cells in tumours exposed to PIT compared to the control groups." (PMID 35057796, 2022). "Our data show that soluble Siglec-5 increased the frequency of IL-2, IFN-γ and TNF-α by MEL624 tumor antigen specific CD4 T cells." (PMID 35290663, 2022). "Previous studies have reported that several immunogenic microenvironment factors, such as T cells (CD4+), macrophages, and mast cells, are prognostic and predictive markers in many tumor types." (PMID 36345339, 2022). "In contrast, more immune cells that promote tumor progression (e.g., CD4+ T regulatory cells, mast cells, and neutrophils) were found in high-risk scoring patients." (PMID 36171881, 2022). "In this state, there are often abundant tumor-associated macrophages and Tregs, which inhibit the function of CD8+T cells and CD4+T cells." (PMID 35368654, 2022). "Previously, we demonstrated that CD4+ T cells were essential to mediate local antitumor immune memory, which led to better long-term survival rates upon local tumor rechallenge." (PMID 35874660, 2022). "The role of OX40 in anti-tumour immunity has been demonstrated by activation of the cytotoxic response through cooperation of CD8+ T cells with CD4+ T cells and the enhancement of CD8-positive cell expansion by direct interaction." (PMID 35328510, 2022). "Neither RT nor PIC + RT treatment showed any significant effect on the expression of PD-1 on tumor-infiltrating CD4+ and CD8+ T cells in these B78 tumors." (PMID 35999216, 2022). "While depletion of other populations including CD4 and NK cells resulted in partial abrogation of tumor control, the depletion of either of these populations alone was not sufficient to eliminate the response of combined therapy." (PMID 36056093, 2022). "The M-MDSC were upregulated in patients (p < 0.0001) and were correlated with CLL tumor progression, poor prognosis, and correlated with the presence of CD4+ T and CD5+CD19+ cells." (PMID 36304465, 2022). "Accumulating evidence suggests that tumor infiltrated lymphocyte (TIL) subpopulations (CD4, CD8, and CD19/20) constitute of both suppressive (pro-tumor) or effector (anti-tumor) phenotypes whose functions are influenced by the surrounding TME." (PMID 36497286, 2022). "For in vivo study, the xenograft tumor tissues of the shSEMA4B and shCtrl group were disaggregated in single-cell suspensions and stained with cell surface markers including CD4, CD25, CD11b, and intracellular markers FOXP3 and Gr1." (PMID 35676688, 2022). "A major role of CD4+ T cells is providing help for anti-tumor cytotoxic T cells through direct and indirect mechanisms." (PMID 35574343, 2022). "CD4+ central memory T cells mainly act on immune memory and immunoprotection during tumor metastasis." (PMID 36619388, 2022). "CellMinor analysis showed that the CD4 mRNA expression level dramatically climbed with increased sensitivity of tumor cells to NAC drugs such as cyclophosphamide, cisplatin, and carboplatin (p’s < 0.05)." (PMID 35433455, 2022). "Increased Treg cells, a particular type of CD4+ T cells, play a crucial role in immune tolerance and tumor progression." (PMID 35155221, 2022). "A subset of CD4+ T cells, such as T-regulatory cells (Tregs), mainly infiltrated in the tumor microenvironment, is considered to be pivotal mediators of peripheral tolerance and immune suppression." (PMID 35711924, 2022). "Thereby, it was shown the versatile role of polyfunctional tumour-infiltrating CD4+ T cells in the overall anti-tumour immune response." (PMID 35406451, 2022). "In this in vitro study NK cells successfully expressed a functional CD4-CD3ζ CAR, which redirected the cells against HIV-infected CD4+ T cells and NK cell-resistant tumor cells." (PMID 35242135, 2022).
tumor (continued). "Intratumoral injection of ex-vivo isolated lymph node podoplanin+ cells, which consists of follicular reticular cells and LECs, promotes tumor growth through the inhibition of tumor-infiltrating CD4+ T lymphocytes." (PMID 35216243, 2022). "In summary, indirect antitumor effects of CD4+ T cells by activating macrophages have been established by several research groups using different tumor models." (PMID 36159781, 2022). "Loss of CD4+ T cells following LAIT treatment had the opposite effect, resulting in delayed tumour growth and prolonged survival in a manner superior to LAIT alone." (PMID 35808806, 2022). "CD4+FoxP3+ Tregs expressing CD39 repressed anti-tumor immunity by NK cells and pharmacologic inhibition of CD39 significantly limited melanoma tumor growth." (PMID 35360246, 2022). "Tumor progression in males and females is associated with a predominant CD8+ > CD4+, Th1 > Th17 > Th2, NKT > NK, M1 > M2 pattern in the liver." (PMID 35235789, 2022). "As altered systemic and local microenvironments, such as immune composition and biomarkers, affect the TIL levels, we next examined the number of infiltrated human CD45+ cells and the ratio of human CD8+ T cells to human CD4+ T cells in the xenografted tumor." (PMID 36358638, 2022). "Here, we report that the coexpression of PD-1 and ICOS (DP CD4+) identified a unique population of CD4+ Th TILs found in the tumor microenvironment (TME)." (PMID 35439168, 2022). "We provide evidence that platelets as well as their tumour cell-induced releasates increased the ratio of regulatory T cells, shaping an immunosuppressive phenotype in isolated CD4+ cultures." (PMID 35285006, 2022). "The anti-tumour effect relied upon direct recognition of tumours by specific CD4+ T cells, suggesting that citrullinated peptides are attractive targets for cancer vaccines." (PMID 36017166, 2022). "A molecule-restrictive neoantigen achieved a durable tumor response after receiving a reactive CD4 T cell transfusion." (PMID 36528587, 2022). "Treatment of OVA-expressing Lewis Lung Carcinoma mice with activin A attenuated tumor progression and heightened the ratio of tumor-infiltrating effectors to regulatory CD4+ T cells." (PMID 35774793, 2022). "Antitumor responses elicited by the combination therapy were dependent on CD4+ and CD8+ T cells and were also associated with the generation of tumor antigen-specific T cells." (PMID 36211806, 2022). "Administration of anti-CTLA-4 antibody gave rise to an enhanced density of tumor-infiltrating CD4 and CD8 T cells." (PMID 35392976, 2022). "As critical mediators in anti-tumor immunity, plasma cells are capable of producing antibodies and CD4+ T cells secrete diverse cytokines that enhance humoral and cellular immunity." (PMID 36568395, 2022). "Gal-9 expression on tumor cells was significantly correlated with CD4 on TILs (P = 0.03), CD8 on TILs (P = 0.03), and PD-L2 (P = 0.02) on tumor cells." (PMID 36263183, 2022). "A number of studies reported that CD4+Foxp3+ regulatory T cell frequency was significantly higher in peripheral blood and tumor tissues of patients with HNSCC than in healthy controls and it was correlated with progression of HNSCC." (PMID 36376825, 2022). "Although the infiltration of tumors by Tregs generally causes a reduction in the immune response to a tumor, infiltration of CD8+ Treg cells has been shown to inhibit naïve CD4+ T cell proliferation via TGF-β and IFN-γ secretion." (PMID 36428581, 2022). "As a first step in our immune cell analysis, we assessed to what extent the CD20 cluster score was associated with abundances of CD4, CD20, or CD21-positive cells in the tumor center or the IM region, both subdivided into tumor and stroma regions." (PMID 36077836, 2022). "The results showed that the expression of CD4 + T cells, neutrophils and macrophages in tumor tissues was significantly higher than in normal tissues." (PMID 36618928, 2022).
tumor (continued). "Tumor spheroids increased the expression of CCR5 on CD4+ T cells, but this significance was lost when both CAFs and tumor spheroids were added." (PMID 35954489, 2022). "We then examined the CD4 levels between higher-CKAP2L tumor tissues and lower-CKAP2L normal tissues." (PMID 36699449, 2022). "For example, studies have found lower CD8+ T-cell densities and higher CD4+/CD8+ ratios in pre-treatment metastatic PDAC tumor samples compared to primary tumor samples." (PMID 36290818, 2022). "In myeloid-derived suppressor cells, expression of membrane-associated RING-CH1 E3 ubiquitin ligase was decreased by inhibiting autophagy, leading to enhanced surface expression of MHC-II and followed by tumor-specific CD4 T cells expansion." (PMID 35761331, 2022). "CXCL9 can bind to CXCR3 expressed in tumor cells to recruit CD4 + T cells, thus promoting the production of CCL5 in TME, promoting tumor invasion." (PMID 36159780, 2022). "Tumor CD4+ T cells showed a significant reduction in number and an increased expression of programmed death-1 (PD-1), and decreased CD107a expression and cytokine such as IFN-γ and TNF-α production, indicating dysfunction." (PMID 36611881, 2022). "By contrast, CD4+ T cells exhibit protective effects in limiting both tumor initiation and tumor progression." (PMID 36612019, 2022). "Compared with mock T cells (CD4+ or CD8+ T cells transduced with lentivirus carrying GFP gene), CD4+ or CD8+ TCR-Ts mediated effective tumor eradication in vivo." (PMID 35928827, 2022). "TslprKO mice received WT (test) or TslprKO (control) CD4+ T cells followed by PyMtOvatg TslprKO tumor implantation." (PMID 35657353, 2022). "We also found that after anti-CD8 antibody treatment, the necrotic area of tumor was reduced, the degree of apoptosis was decreased, and the infiltration of CD4+ and CD8+ T cells was also reduced, observed using immunohistochemical methods." (PMID 35547769, 2022). "CaMKK2 promotes exhaustion in CD8+ T cells and reduces the expansion of effector CD4+ T cells, additionally limiting their tumor penetrance." (PMID 36309495, 2022). "IFIT2 was significantly inversely correlated with tumor purity (p = 9.77e-05), B cells (p = 9.68e-03), CD4+ T cells (p = 7.10e-04), macrophages (p = 2.20e-03) and neutrophils (p = 6.34e-03)." (PMID 36386128, 2022). "Tumor immunosuppressive cells including M2 macrophages, MDSCs and Treg can multiply while effector CD4+ and CD8+ T lymphocytes are inhibited from doing so by IL-10 and TGF-β." (PMID 36439472, 2022). "Within these two gene sets, we found that ERG- patient-enriched CD4 T-cells, tumor cells, and stromal cells showed significantly higher expression of a family of HLA genes compared to ERG+ cell populations (P < 0.05, Wilcoxon rank-sum test)." (PMID 35013146, 2022). "CD25+CD4+ TIL from RencaHA tumor-bearing mice suppressed in vitro proliferation of naïve CL4 T cells in a manner dependent on the adenosine 2A receptor (A2AR)." (PMID 35013519, 2022). "There was enhanced breast tumor progression in CD4-NFAT5-KO mice, suggesting that NFAT5 knock out abrogated the inflammatory anti-tumor activation of CD4+T cells." (PMID 35741331, 2022). "TNFSF4, also known as OX-40L, is a member of the TNF superfamily, which provides signals for CD4 T cell responses and plays an important role in tumor immunotherapy." (PMID 35804089, 2022). "Historically, CD8+ T cell–mediated killing is thought to occur predominantly via the perforin-granzyme B pathway, whereas CD4+ T cell–mediated killing is thought to rely on activation of the death receptor Fas on tumor cells by Fas ligand expressed on T cells." (PMID 36271507, 2022). "Taken together, these studies suggest that physiologic sources of HGFL support mammary tumorigenesis by promoting tumor cell proliferation, limiting tumor cell death, recruiting M2 (Arginase-1+) macrophages, and suppressing CD4+ and CD8a+ T cell recruitment." (PMID 35626096, 2022).